CA9 (carbonic anhydrase 9)
Diseases named in the same sentence as CA9 in open-access papers (continued):
Sharing a sentence is not in itself a finding about the gene and the disease.
breast carcinoma (continued). "Furthermore, in a panel of 16 pancreatic cancer cell lines and 21 breast cancer cell lines, NCCRP1 and CA9 expression were inversely correlated in certain cell lines; NCCRP1 was weakly expressed or absent when CA9 mRNA was highly expressed, and vice versa." (PMID 22087255, 2011). "Furthermore, we found that the basal breast cancer cell lines also exhibited elevated expression levels of three hypoxia-inducible genes (VEGF, GLUT1, and CA9) even under normoxia." (PMID 21672245, 2011). "Whereas it is likely that patients with Basal-like breast cancer could benefit from CA9- and CA13-targeted therapy, our current findings show that patients with HER2-enriched breast cancer will likely follow a more severe disease trajectory if treated with a carbonic anhydrase inhibitor." (PMID 37098526, 2023). "Finally, we investigated whether there was any link between the expression of WSB1 and HIF targets SLC2A1, VEGFA, CA9, and HK2 in breast cancer patients." (PMID 29540773, 2018). "In order to further explore whether Treg recruitment was associated with hypoxia or other factors expressed by the basal subtype, we correlated Treg numbers with CA9 expression in a subset of 327 non-basal breast cancers." (PMID 21521526, 2011). "Furthermore, 51% of breast cancer skin deposits grows according to a less angiogenic infiltrative pattern with lower microvessel density, endothelial cell proliferation fraction (ECP%) and CA9 expression." (PMID 16251878, 2005). "This differential effect of CO2/HCO3– at the core and periphery of breast cancer organoids is abrogated when intra- and extracellular carbonic anhydrases are inhibited with acetazolamide but not when only extracellular carbonic anhydrases or CA9 are inhibited with AMB and FC5-207A, respectively." (PMID 37098526, 2023).
renal cell carcinoma (150 papers, 2001 to 2025). "Molecular biology methods can detect kidney cancer-related markers in urine or blood, such as DNA microsatellite alterations, VHL gene mutations or hypermethylation, renal cell carcinoma-specific proteins such as CA-9 expression, and upregulation of angiogenic factors such as VEGF expression." (PMID 37138262, 2023). "As a proof-of-principle we first assessed DATE specificity in patient-derived models of ccRCC where CA9 is constitutively expressed, irrespective of oxygen tension, due to VHL loss (RCC243) and in the murine cortical adenocarcinoma renal cell carcinoma cell line (Renca) where we overexpressed CA9." (PMID 35874663, 2022). "Previous studies have reported that CA9 encodes HLA class I‐ and HLA class II‐restricted epitopes that could be recognized by helper T cells in renal cell carcinoma." (PMID 32299152, 2020). "Furthermore, another SNP in CA9 (rs12553173) was independently associated with improved overall survival and greater likelihood of response to therapy in renal cell carcinoma, thus warranting further functional analysis." (PMID 28143503, 2017). "In conclusion, hMOF as an acetyltransferase of H4K16 might be involved in the pathogenesis of renal cell carcinoma, and this epigenetic change might be a new CA9-independent RCC diagnostic marker." (PMID 23394073, 2013). "Our diagnosis also excluded sarcomatoid transformation of renal cell carcinoma and urothelial carcinoma through CA9, Pax-8, GATA3, P63, and P40." (PMID 40978053, 2025). "Girentuximab is a carbonic anhydrase 9–targeted monoclonal antibody with 89Zr PET imaging paired with 177Lu or 225Ac therapy in renal cell carcinoma." (PMID 41344832, 2025). "This mAb binds the tumor-associated antigen Carbonic Anhydrase 9 (CAIX), a transmembrane enzyme expressed by Renal Cell Carcinoma (RCC) and hypoxic tumor cells, while rarely found in healthy organs." (PMID 38125888, 2023). "A panel of immunohistochemistry markers useful to distinguish TFE3/TFEB-rearranged renal cell carcinoma from other common renal cell neoplasms should include cathepsin K, CA9, CK7, and parvalbumin." (PMID 35980471, 2022). "Previous research found that inhibition of CA9 increases sensitivity of renal cell carcinoma to ionizing radiation." (PMID 32824856, 2020). "Binding to CA9 and internalization of positron emission tomography (PET) tracers labeled with CA9 antibody have been demonstrated in a mouse xenograft model of renal cell carcinoma." (PMID 33007872, 2020). "In patients with renal cell carcinoma, a statistically significant increase in the level of Tu M2-PK, CA9 and a statistically significant decrease in MMP9 in comparison with the control group were found." (PMID 34513052, 2020). "It has been observed that exosomes derived from renal cell carcinoma (RCC) cells are enriched with carbonic anhydrase 9 (CA9), a downstream target of HIF‐α, and promote human umbilical vein endothelial cell (HUVEC) migration and tube formation through CA9‐mediated MMP‐2 upregulation." (PMID 36786037, 2023). "In conclusion, since TFE3/TFEB-rearranged renal cell carcinoma may mimic several histotypes, an immunohistochemical panel to differentiate them from common renal cell tumors should include cathepsin K, CA9, CK7, and parvalbumin." (PMID 35980471, 2022). "CA9 can serve as a potential target for renal cell carcinoma-specific immunotherapy." (PMID 36330810, 2022). "However, staining for CD10 has an important value in the differential diagnosis with TFEB-rearranged renal cell carcinoma, along with cathepsin K and CA9." (PMID 35980471, 2022). "Furthermore, CA9 inhibition sensitizes colorectal carcinoma and renal cell carcinoma to irradiation, and induces ferroptosis in malignant mesothelioma." (PMID 32824856, 2020). "CA-9 is upregulated in hypoxic conditions and has been shown to play a role in tumorigenesis by altering pH to promote tumor growth and survival in a number of tumors, notably renal cell carcinoma." (PMID 30340515, 2018).
renal cell carcinoma (continued). "In fact, genetic association studies that included the CA9 + 201 A > G polymorphism showed neither risk for renal cell carcinoma nor for oral squamous cell carcinoma." (PMID 28143503, 2017). "Meta-analyses have also shown high tumour expression of CA9 is an adverse prognostic factor in multiple cancers: renal cell carcinoma [RCC] (n=2,611), oral squamous cell carcinoma [OSSC] (n=1,616), and head and neck [H&N] cancer (n=1,470)." (PMID 38352889, 2024). "Indeed, a monoclonal antibody against CA9 (gerentuximab) has shown considerable promise in renal cell carcinoma and may be suitable for NSCLC patients with PET intense tumors." (PMID 29966011, 2018). "Likewise, a recent report described lack of association between the CA9 + 201 SNP with CAIX protein expression in renal cell carcinoma." (PMID 28143503, 2017). "The presented results strongly indicate the potential significance of the Tu M2-PK, CA9, and MMP9 proteins as markers capable of predicting the disease course in patients with renal cell carcinoma." (PMID 34513052, 2020). "The results indicate a potential significance of Tu M2-PK, CA9, and MMP9 as biological markers for predicting the disease course in patients with renal cell carcinoma." (PMID 34513052, 2020). "In renal cell carcinomas, VHL inactivation occurs in most sporadic cases, resulting in an accumulation of CA9, HIF-1α and HIF-2α." (PMID 15558070, 2005). "CA9 is usually negative either in TFE3 or TFEB-rearranged renal cell carcinoma whereas it is an important positive reliable marker in clear cell renal cell carcinoma." (PMID 35980471, 2022). "Considering other markers commonly evaluated when dealing with renal cell carcinomas, CA9 was expressed by 6 of 35 (17%), 2 of 35 (6%), and none of 35 (0%) MiT family translocation renal cell carcinomas, respectively, using a 5%, 10%, and 20% cutoff." (PMID 35980471, 2022). "The aim of the study was to assess the possibility of using plasma levels of tumor M2-pyruvate kinase (Tu M2-PK), matrix carbonic anhydrase IX (CA9), and matrix metalloproteinase 9 (MMP9) in patients with renal cell cancer as predictors of the disease course and the response to treatment." (PMID 34513052, 2020). "in renal cell carcinomas, 74 samples of blood and tissue from patients were analysed, and CA9 expression was detected in 24 of them, with a specificity of 100%, with no CA9-positive sample among the control patients." (PMID 29745265, 2018). "Namely, whereas CA9 immunolabeling was found in 6 of 25 (24%) TFE3-rearranged renal cell carcinomas with a 5% threshold, in 2 of them (8%) and none of them (0%), respectively, referring to a 10% and 20% cutoff, all the TFEB-rearranged renal cell carcinomas were negative for such marker." (PMID 35980471, 2022). "CA9, a transmembrane member of the carbonic anhydrase family, is not expressed in healthy and benign renal tissues, but it is present in 91.2% of clear cell renal cell carcinomas (CCRCC), which make up 75% of RCC, by IHC analysis." (PMID 27494883, 2016). "Basically, translocation renal cell carcinoma is labeled for cathepsin K and HMB45 while it is negative for CA9 and CK7." (PMID 35980471, 2022). "Among the commonly used immunohistochemical markers, CA9 and cytokeratin 7 are the most helpful immunostainings for differentiating TFE3-rearranged renal cell carcinoma from common renal cell tumors as they are frequently negative in TFE3-rearranged renal cell carcinoma." (PMID 39410016, 2024).
cervical carcinoma (78 papers, 2003 to 2025). A carcinoma arising from either the exocervical squamous epithelium or the endocervical glandular epithelium. "Another non-coding variant located in the 3'-untranslated region of CA9 gene, rs1048638, has been demonstrated to affect the susceptibility to liver 16 and cervical cancer." (PMID 35812185, 2022). "This explains the decreased binding of miR-34a with the 3′-UTR of exon 11 of CA9, where the CA9 SNP rs1048638 is located, in women with cervical cancer with the mutant allele A in the CA9 SNP rs1048638 and the elevated CAIX expression in Taiwanese women." (PMID 29100431, 2017). "To confirm the importance of the rs1048638 polymorphism in the regulation of CA9 expression by miR-34a, we examined the rs1048638 genotypes of three cervical cancer cell lines (HeLa, SiHa, and Caski)." (PMID 29100431, 2017). "In high risk, early stage cervical cancer, CA9 is an independent prognostic factor for both progression free survival and overall survival." (PMID 24349364, 2013). "In addition, this is consistent with previous finding that CA9 increased the risk of cervical cancer, we found that CA9 played a crucial role in cervical cancer progression." (PMID 36313765, 2022). "Furthermore, we observed that only one mutant allele A is sufficiently strong to increase the risk of cervical cancer in the CA9 SNP rs1048638 based on the analysis of the allele distribution for CA9 SNPs." (PMID 29100431, 2017). "In conclusion, our study reveals that the CA9 SNP rs1048638 is the only significant polymorphism that increases the risk of cervical cancer among four CA9 gene polymorphisms, rs2071676 (+201, G/A), rs3829078 (+1081, A/G), rs1048638 (+1584), and an 18-base pair deletion/insertion, in Taiwanese women." (PMID 29100431, 2017). "We further delineated the mechanism by which CA9 SNPs may influence the expression of CAIX in cervical cancer and associated the CAIX expression with the clinicopathological variables, cancer recurrence, and survival of patients with cervical cancer." (PMID 29100431, 2017). "The results suggested that CA9 played a crucial role in the occurrence and development of cervical cancer." (PMID 36313765, 2022). "Here we found that it also had the potential to treat cervical cancer, in a mechanism involving CA9, TFRC, and SCD." (PMID 36313765, 2022). "Four genes were linked to the prognosis of ferroptosis in cervical cancer, namely, RNF130, CA9, DERL3, and VEGFA, which were obtained by univariate Cox regression analysis in the training set." (PMID 35935576, 2022). "SCD and TFRC were expressed in both normal cervical and cervical cancer tissues, while CA9 was expressed in only cervical cancer tissues." (PMID 36313765, 2022). "Based on the results, we further analyzed CA9, hoping to clarify the mechanism in the involvement of CA9 of ferroptosis in cervical cancer." (PMID 36313765, 2022). "Cervical cancer with a high expression of CA9 has a higher rate of local recurrence and distant metastasis and is closely related to the poor prognosis of early cervical cancer." (PMID 34030694, 2021). "In cervical cancer, a high expression level of HIF-1α and its downstream target, the tumor-associated cell-surface glycoprotein carbonic anhydrase 9 (CA9), is linked with poor prognosis and therapy resistance." (PMID 34830902, 2021). "According to our review of the relevant literature, few studies have correlated CA9 SNPs with cervical cancer." (PMID 29100431, 2017). "We used the Boyden chamber assay to evaluate the influence of CA9 on the migration of cervical cancers." (PMID 29100431, 2017). "Transfection with themiR-34a mimic led to changes in the miRNA–mRNA duplex interaction in the CA9 SNP rs1048638 and reduced the CAIX expression, which reduced the migratory abilities of HeLa and SiHa cervical cancer cells." (PMID 29100431, 2017). "A significant difference was observed in the distribution of the CA9 SNP rs1048638 (p = 0.011) between women with cervical cancer and controls." (PMID 29100431, 2017).
cervical carcinoma (continued). "CA9 has been reported as a poor prognostic marker in cervix cancer, although a number of studies have found evidence for a correlation." (PMID 27901496, 2017). "We demonstrate a direct in vivo functional link between the CA9 positive fractions in primary cervix cancer xenografts and their content of CICs." (PMID 27901496, 2017). "A recent study has reported very limited concordance between pimonidazole staining and CA9 expression in two transplantable cervix cancer xenografts further emphasizing the heterogeneity in tumours." (PMID 27901496, 2017). "We used early passage primary cervix cancer xenografts to sort cells based on the expression of the intrinsic hypoxia marker Carbonic Anhydrase 9 (CA9) and tested their cancer initiation potential by limiting dilution assay." (PMID 27901496, 2017). "A previous report exhibited a predominantly positive correlation between CA9 expressions and the levels of tumor hypoxia in cervical carcinoma." (PMID 26447758, 2015). "High levels of CA9 in plasma and serum have been measured to be raised in the patients with breast, lung, gastric and cervical cancer." (PMID 26447758, 2015). "The correlation between clinical outcomes and CA9 expression have been reported with several other malignancies including cancer of the cervix, lung, breast and head and neck." (PMID 19619339, 2009). "Hypoxia has been shown to induce CA-9 protein in vitro, and CA-9 has been shown to correlate with hypoxia measured by Eppendorf histography in carcinoma of the cervix." (PMID 16404365, 2006). "Biopsies of invasive cervical carcinomas also showed a good correlation between staining for the two hypoxia markers, CA9 staining being more extensive in almost all cases." (PMID 12838292, 2003). "CA9, TFRC and SCD are all risk factors for cervical cancer, so we predicted candidate drugs for these genes, among which 2-(4-morpholinyl)-8-phenyl-4H-1-benzopyran-4-one and oxygen could regulate all three of these risk factors." (PMID 36313765, 2022). "Further research found that the ceRNA pairs of ULBP2/CA9 could regulate cervical cancer through hsa-miR-34a." (PMID 36313765, 2022). "However, CA9, DERL3, and VEGFA genes were all upregulated while the opposite was reported for RNF130 in cervical cancer and was linked to unsatisfactory prognosis in the present research." (PMID 35935576, 2022). "Subsequently, we wanted to know how CA9 works in cervical cancer, then we found that CA9/ULBP2 ceRNA network may be a key mechanism in the pathogenesis of cervical cancer." (PMID 36313765, 2022). "However, the limitation of our study is that it has not been confirmed by the experimental results, but this is what our research group will do next, hoping to truly enrich the pathogenesis of CA9 of cervical cancer and apply the theory into practice." (PMID 36313765, 2022). "Together, the results suggested that CA9, TFRC, and SCD were risk factors for cervical cancer." (PMID 36313765, 2022). "CA9 is considered to be a new specific biomarker for cervical cancer hypoxic cells." (PMID 34030694, 2021). "In addition to the evidence for correlations between CA9 and RHOA functions, CA9 has also been found to promote cervical cancer cell invasions by inhibiting RHOA in vitro." (PMID 30034621, 2018). "In conclusion, the finding that the CA9 SNP rs1048638 exerts its action through duplexes of the miR-34a and CA9 3′-UTRs and plays a vital role in cervical cancer in Taiwanese women may be applicable to translational medicine." (PMID 29100431, 2017). "Furthermore we, (and others) have previously reported that CA9, an hypoxia surface marker, can be successfully used to sort hypoxic cervical carcinoma cells originating from cell line-derived xenografts." (PMID 27901496, 2017). "The mRNA expression of CA9 was the highest in Caski and the lowest in SiHa cervical cancer cells." (PMID 29100431, 2017).